HERPUD1 (homocysteine inducible ER protein with ubiquitin like domain 1)
Diseases named in the same sentence as HERPUD1 in open-access papers (continued):
Sharing a sentence is not in itself a finding about the gene and the disease.
liver cancer (1 paper, 2022). An epithelial or non-epithelial malignant neoplasm that arises from the liver. "In this study, we found that CA increased the sensitivity of liver cancer cells to ferroptosis by upregulating HERPUD1." (PMID 36038536, 2022). "In conclusion, our data are the first to show that CA can increase the sensitivity of liver cancer cells to ferroptosis by upregulating HERPUD1." (PMID 36038536, 2022). "From gene and protein levels, we showed that CA increased the sensitivity of liver cancer cells to ferroptosis by upregulating HERPUD1." (PMID 36038536, 2022). "Here, we revealed that CA can inhibit glutathione (GSH) synthesis via HERPUD1, decreasing the cellular GSH level and causing liver cancer cells to become more sensitive to ferroptosis." (PMID 36038536, 2022). "We found that HERPUD1 reduces MDM2 ubiquitination in liver cancer cells, while MDM2 induces the ubiquitination of GSS, thereby reducing the content of GSS, and finally inhibiting the synthesis of GSH to increase ferroptosis." (PMID 36038536, 2022). "The results of cycloheximide (CHX) chase experiment showed that the half-life of GSS was prolonged in liver cancer cells after HERPUD1 was knocked out." (PMID 36038536, 2022). "Liver cancer cells that knockout HERPUD1 produced less lipid reactive oxygen species and cell death after treatment with the CA or ferroptosis inducers." (PMID 36038536, 2022). "We confirmed that CA increases the sensitivity of liver cancer cells to ferroptosis through HERPUD1." (PMID 36038536, 2022). "The key gene HERPUD1 that CA increases the ferroptosis sensitivity of liver cancer cells was screened by RNA-seq and TMT." (PMID 36038536, 2022). "We next investigated the mechanism of how CA increases the sensitivity of liver cancer cells to ferroptosis through HERPUD1." (PMID 36038536, 2022). "Next, we examined whether HERPUD1 played a vital role in increasing the sensitivity of liver cancer cells to ferroptosis following CA treatment." (PMID 36038536, 2022). "The knockout efficiency of HERPUD1 was verified in two liver cancer cell lines." (PMID 36038536, 2022). "However, the role of HERPUD1 in liver cancer and ferroptosis is less clear." (PMID 36038536, 2022). "Furthermore, we investigated the mechanism by which CA increases the ferroptosis sensitivity of human liver cancer cells, and revealed that CA sensitized ferroptosis by upregulating Homocysteine inducible ER protein with ubiquitin-like domain 1 (HERPUD1) in liver cancer cells." (PMID 36038536, 2022). "In HERPUD1-sg1 liver cancer cells, the content of GSH in the same treatment group was significantly higher than that in WT liver cancer cells." (PMID 36038536, 2022). "Compared with normal liver cancer cells, the ubiquitination of MDM2 was increased in HERPUD1-sg1 liver cancer cells by co-IP experiments, and the half-life of MDM2 was prolonged in liver cancer cells knocked out HERPUD1 by CHX chase experiments." (PMID 36038536, 2022). "In addition, Fe2+ content in the same treatment did not change significantly in WT and HERPUD1-sg1 liver cancer cells." (PMID 36038536, 2022).
neuroblastoma (1 paper, 2022). Neuroblastoma (NB) is the most common solid, extracranial childhood tumor. "HSPA5, HERPUD1, and CLU expression increased in vivo and cultured neuroblastoma cells." (PMID 35984750, 2022).
periodontitis (1 paper, 2024). An acute or chronic inflammatory process that affects the tissues that surround and support the teeth. "The ferroptosis-related genes identified in this study, including SLC1A5, SLC2A14, LURAP1L, and HERPUD1, may serve as novel diagnostic and therapeutic targets for periodontitis." (PMID 38802844, 2024). "The ANN diagnostic model comprising four key genes—SLC1A5, SLC2A14, LURAP1L, and HERPUD1—demonstrated a high predictive efficacy for periodontitis with an AUC of 0.928 in the dataset." (PMID 38802844, 2024). "The ferroptosis-related genes SLC1A5, SLC2A14, LURAP1L, and HERPUD1 may serve as novel biomarkers for the diagnosis of periodontitis." (PMID 38802844, 2024). "Based on this, our study hypothesizes that ferroptosis-related genes, including SLC1A5, SLC2A14, LURAP1L, and HERPUD1, could be novel biomarkers for periodontitis." (PMID 38802844, 2024). "Subsequently, through protein–protein interaction networks and multi-dataset machine learning algorithms, we further narrowed down these candidates to four key ferroptosis-related genes differentially expressed in periodontitis, namely SLC1A5, SLC2A14, LURAP1L, and HERPUD1." (PMID 38802844, 2024).
Polypoidal choroidal vasculopathy (1 paper, 2024). The presence of aneurysmal 'polypoidal' lesions in the choroidal vasculature. "Polymorphism in the Herpud1 gene was associated with polypoidal choroidal vasculopathy and HERPUD1 was expressed in the subretinal vascular membranes." (PMID 39453673, 2024).
renal failure (1 paper, 2017). "Because complete Herpud1-knockout mice were used in the present study, it is difficult to rule out the participation of other organs or extra-cardiac processes, such as increased blood pressure or renal failure, in triggering the observed hypertrophic phenotype." (PMID 29042597, 2017).
Sepsis (1 paper, 2025). Sepsis is defined as life-threatening organ dysfunction caused by a dysregulated host response to infection. "Similarly, the expression levels of XBP1 and Herpud1 demonstrated a positive correlation with each other in sepsis." (PMID 40867920, 2025). "XBP1 and HERPUD1 (p = 0.012) exhibited a negative correlation with sepsis score while demonstrating a significant positive correlation with one another." (PMID 40867920, 2025). "Moreover, the downregulation of genes with a protective role against OS, such as XBP1, HERPUD1, and SELENOS in septic foals, underscores their importance in alleviating OS in addressing sepsis." (PMID 40867920, 2025). "Additionally, the downregulation of genes with protective function against OS, such as XBP1, HERPUD1, and SELENOS, in septic foals also highlights their significance in mitigating OS in sepsis treatment." (PMID 40867920, 2025). "In the present study, several genes associated with ER stress, including XBP1, HERPUD1, LRRK2, and SELENOS, were downregulated in foals suffering from sepsis, showing a negative correlation with the sepsis score." (PMID 40867920, 2025). "In the present septic foal study, expression levels of both XBP1 and Herpud1 decreased and exhibited a negative correlation with the sepsis score while showing a positive correlation with one another." (PMID 40867920, 2025). "In contrast, XBP1 (p = 0.002), HERPUD1 (p = 0.002), LRRK2 (p = 0.015), and SELENOS (p = 0.008) showed a significant negative correlation with sepsis score." (PMID 40867920, 2025). "Conversely, XBP1, HERPUD1, LRRK2, and SELENOS exhibited a negative correlation with sepsis scores and a positive correlation with the combined activities of antioxidant enzymes, highlighting the potential of ER stress as a novel therapeutic target and prognostic marker in septic foals." (PMID 40867920, 2025).
vitiligo (1 paper, 2025). Generalized well circumscribed patches of leukoderma that are generally distributed over symmetric body locations and is due to autoimmune destruction of melanocytes. "Finally, we obtained ten matched genes (GP1BA, ANKS4B, CCDC87, CA8, HLA‐DOB, RHEBL1, NLRP7, GZMH, HERPUD1, and MAP2K1) as a vitiligo‐gene signature (VGS)." (PMID 40974370, 2025).
ZIKV infection (1 paper, 2021). "It is unclear whether HERPUD1 upregulation is prevented during ZIKV infection in trophoblasts to ensure a productive infection by avoiding any innate immune response." (PMID 33500388, 2021).
tumor (22 papers, 2015 to 2026). "In TNBC, in addition to epithelial cells, HERPUD1 associated with inflammatory infiltrates, highlighting its potential role in tumor progression." (PMID 41193432, 2025). "Altogether, suggesting that HERPUD1 may play a role in tumor-associated immunity and should be further investigated in this context." (PMID 41193432, 2025). "Quantification confirmed a consistent decrease in spheroid area in HERPUD1 KD cells, indicating that HERPUD1 supports the structural integrity and growth properties of tumor cells in a 3D environment." (PMID 41193432, 2025). "We also show that HERPUD1 contributes to tumor aggressiveness in 2D and 3D models by promoting proliferation, migration, invasion, and cell survival in response to doxorubicin (DOX)." (PMID 41193432, 2025). "HERPUD1’s role in cancer progression is context-dependent, displaying tumor-suppressive or pro-tumoral functions in different tissues and tumor microenvironments." (PMID 41193432, 2025). "The expression analysis of key genes (PNRC1, HERPUD1, TP53INP2, Tob1, and SAT1), which is typically silenced in various tumour tissues and associated with poor prognosis and short survival time, revealed their upregulation upon 24 h treatment with L1." (PMID 39861074, 2024). "A study found that HERPUD1 mRNA is significantly downregulated in metastatic prostate cancer, which effectively predicts the occurrence of tumor metastasis." (PMID 36544104, 2022). "In the present study, we found that the expression of Lewis y and HERPUD1 was significantly correlated in the early stage of tumor, and proves that Lewis y regulates the expression of HERPUD1." (PMID 36544104, 2022). "Under suboptimal cultivation conditions (no filter support or low oxygen with filter support), the down-regulation of BRCA1 and BLM (DDR) and up-regulation of HERPUD1 was common to slices from all three tumour xenograft models." (PMID 26647838, 2015). "Therefore, the potential role of HERPUD1 within the immune tumor microenvironment remains an open question that should be addressed in future studies." (PMID 41193432, 2025). "To explore HERPUD1 regulation under ER stress, we analyzed its expression in different BC lines exposed to chemical stress and lipid-induced stress, as experimental paradigms modeling key features of the tumor microenvironment." (PMID 41193432, 2025). "Moreover, HERPUD1 overexpression inhibits tumor cell proliferation, suppresses EMT, enhances the response to chemotherapy, and reduces macrophage and neutrophil polarization, likely contributing to a more immunoreactive tumor microenvironment." (PMID 41193432, 2025). "Moreover, we unveiled co‐occurrence relationships among ITSGs in tumour mutations, such as TIPARP with DDX3X and HERPUD1 with DNAJB1." (PMID 39031800, 2024). "The authors proposed that HERPUD1 may function as a tumour suppressor, inhibiting tumourigenesis, and could serve as a promising molecular target for new and effective anticancer therapy." (PMID 39861074, 2024). "The high expression of HERPUD1 decreased with advance stages (P = 0.016), which is consistent with GEPIA website results, indicating that HERPUD1 may be more effective in the early stages of the tumor." (PMID 36544104, 2022). "Here, we investigated whether HERPUD1 contributes to the invasive capabilities of tumor cells." (PMID 41193432, 2025). "Importantly, a mouse xenograft model also demonstrated that CA inhibits tumor growth via HERPUD1." (PMID 36038536, 2022). "Furthermore, we used regression coefficients for HERPUD1, MAP3K8, GAPDH, and DNAJB4 to construct risk score models as follows: risk score = −0.197∗MAP3K8 −0.261∗HERPUD1+ 0.185∗GAPDH+ 0.191∗DNAJB4 and calculated the risk score for each LUAD tumor sample." (PMID 34295900, 2021).
tumor (continued). "Among the identified five distinct macrophage subpopulations (FCN1+Inflam-Mac, PRDX1+LA-Mac, HERPUD1+LA-Mac, ALOX5AP+LA-Mac and OxP-Mac), OxP-Mac predominantly enriched in normal kidney tissues, whereas the other subtypes were mainly found in tumor regions." (PMID 41601657, 2026). "Pseudotime trajectory analysis positioned OxP-Mac as an early-state population branching into tumor-specific subsets (ALOX5AP+, HERPUD1+ and PRDX1+LA-Mac), suggesting differentiation plasticity." (PMID 41601657, 2026). "In contrast, the tumor-enriched PRDX1+ and HERPUD1+LA-Mac subtypes displayed mixed M1/M2 signatures, suggesting alternative activation states beyond the canonical M1/M2 classification." (PMID 41601657, 2026). "In xenografts, CA±IKE lowers tumor growth and GSH; HERPUD1 knockout blunts effects and reduces GSS ubiquitination." (PMID 41140341, 2025). "Our findings establish HERPUD1 as a key mediator of PA-driven aggressiveness, dependent on the lipid-handling capacity of TNBC cells and reveals a mechanistic to lipid stress and tumor progression." (PMID 41193432, 2025). "IP, HERPUD1, GADD34, HMOX1, and MANF mRNA levels were significantly upregulated in tumor samples, indicating robust activation of all three arms of the UPR." (PMID 41120732, 2025). "FKBP4, TK1, HERPUD1, and CLEC3B levels were measured and verified in clinical samples (tumor tissues)." (PMID 37341998, 2023). "The upregulated ACSL3, DDIT4, RRM2, and SLC2A1 with HR > 1 were considered as oncogenes, whereas the downregulated HERPUD1 and PEBP1 with HR < 1 were regarded as tumor suppressors." (PMID 34499810, 2021). "Functional polarization analysis showed these macrophage sub types were not canonical M1/M2 features, while tumor-enriched PRDX1+ and HERPUD1+LA-Mac exhibited mixed M1/M2 features." (PMID 41601657, 2026).
cancer (14 papers, 2014 to 2025). A tumor composed of atypical neoplastic, often pleomorphic cells that invade other tissues. "Specifically, HERPUD1 silencing reduced the levels of IL-6 and IL-8, known to promote cancer stem cell expansion and chemoresistance, in response to PA." (PMID 41193432, 2025). "HERPUD1’s involvement in ferroptosis has been demonstrated in various cancers, suggesting a broad role in this cell death mechanism." (PMID 39857625, 2024). "In the present study, knocking down HERPUD1 in cancer cell lines resulted in a significant decrease in the proliferation of these cells." (PMID 36544104, 2022). "Recent studies also indentify Herpud1 as cytoprotective factor against oxidative stress in cancer cells." (PMID 28430789, 2017). "HERPUD1 is a protein of the endoplasmic reticulum (ER) that is sensitive to the unfolded protein response (UPR) induced during ER stress and has been linked to ER stress tolerance in cancer cells." (PMID 41193432, 2025). "An important question that arises from all these observations is whether HERPUD1 is under the regulation of a biochemical or molecular system that may offer anti-cancer therapeutic opportunities." (PMID 41193432, 2025). "For example, an aberrant HERPUD1 expression has been reported for ovarian and liver cancers." (PMID 37297004, 2023). "HERPUD1 is implicated in ovarian and liver cancers, whereas no data link HERPUD1 to MM." (PMID 37297004, 2023). "A set of genes, including PNRC1, HERPUD1, TP53INP2, Tob1, and SAT1, were downregulated in patients with different cancer types, and their decreased expression was correlated with poorer prognosis and shorter survival time." (PMID 39861074, 2024). "In the TA of LLC‐bearing mice, a model of cancer cachexia but in C57BL/6 background, the mRNA levels of p47, Ufd2, Nploc4, and Herpud1 were all induced by about 50%, while Ufd1, Derl1, Rnf31, and Hsp90 did not change." (PMID 35611892, 2022). "Therefore, HERPUD1 is not merely a stress response protein but also a key regulator of cellular plasticity involved in cancer progression." (PMID 41193432, 2025).
infection (4 papers, 2012 to 2023). The state of being infected such as from the introduction of a foreign agent such as serum, vaccine, antigenic substance or organism. "Induction of Herpud1 was lost upon infection with UV-inactivated virus, consistent with viral gene expression being required for the induction of the ER stress response." (PMID 22969428, 2012). "Interestingly, in infected wild-type cells, Herpud1, Sel1L and calreticulin underwent rapid degradation following infection in wild-type and rUbe2g2WT cells, which was blocked in both the Ube2g2−/− and rUbe2g2C89K cells with increase in synthesis over time." (PMID 37164963, 2023).
cardiovascular disease (2 papers, 2014 to 2021). "HERPUD1 (homocysteine inducible endoplasmic reticulum (ER) protein with ubiquitin like domain 1) is important in the ER stress response, which influences a number of diseases, including neurodegeneration and cardiovascular disease." (PMID 33623715, 2021).
HERPUD1 also shares sentences with these, for which no sentence is quoted: Parkinson disease (3 papers); Alzheimer disease (2); bladder cancer (2); depression (2); glioblastoma (2); Lipedema (2); Anxiety (1); autoimmune disease (1); central nervous system disorder (1); chronic obstructive pulmonary disease (1); coronary artery disease (1); diabetics (1); hepatoma (1); Hyperglycemia (1); Hypertension (1); ischemic cardiomyopathy (1); liver cirrhosis (1); movement disorder (1); muscular disease (1); Obesity (1); ocular hypertension (1); oral cancer (1); oral squamous cell carcinomas (1); ovarian serous cystadenocarcinoma (1); pancreatic cancer (1); Pca (1); Peripheral edema (1); preeclampsia (1); restless legs syndrome (1); schizoaffective disorder (1).
A further 1 disease shares a sentence with HERPUD1 in 1 paper.